BRAF (B-Raf proto-oncogene, serine/threonine kinase)
Diseases named in the same sentence as BRAF in open-access papers (continued):
Sharing a sentence is not in itself a finding about the gene and the disease.
melanoma (continued). "Silencing of CDK16 through shRNA inhibited the growth of BRAF‐mutant melanoma cell lines in vitro and in vivo." (PMID 29112787, 2018). "Consistently, OXPHOS inhibitors decrease the prevalence of BRAF inhibitor-resistant slow-cycling melanoma cells." (PMID 29534029, 2018). "On the other hand, nutrient metabolism interferes with responsiveness to BRAF (kinase) inhibition in melanoma and other tumors." (PMID 29794999, 2018). "In the present study, we established a PDOX nude mouse model with a BRAF-V600E-negative melanoma from a patient." (PMID 29416666, 2018). "Most cutaneous melanomas harbor activating mutations in the protein kinase BRAF, which makes inhibitors that target mutant BRAF promising agents to treat melanoma patients." (PMID 30456204, 2018). "A 46 year old male who presented in 2006 with a 3.7 mm BT (Breslow thickness), BRAF wild-type melanoma on his left forearm." (PMID 30107850, 2018). "One patient whose primary melanoma tumor was reported to be wild‐type for BRAF (COBAS Real‐Time Polymerase Chain Reaction performed in a CLIA‐approved Molecular Diagnostics Laboratory) was found to have a circulating BRAF V600E mutation." (PMID 30113761, 2018). "solTNF-mediated induction of MAPKi resistance in BRAF-V600E-mutant melanomas is predicated on the co-expression of TNFR1 and TNFR2." (PMID 30400822, 2018). "Of interest, an olive leaf extract enriched in equimolar Ole was more effective and able to further improve DTIC and RAD001 efficacy on BRAF melanoma cells with respect to Ole alone." (PMID 30544808, 2018). "Nevertheless, melanoma cells adapt to the block of BRAF and MEK, becoming able to thrive even under pharmacological pressure." (PMID 30558661, 2018). "Our study shows that BRAF inhibition triggers a response, which protects drug-responsive melanoma cells and thereby mediates resilience." (PMID 30237393, 2018). "The best combination in inducing cell death on BRAF A375 melanoma cells was represented by the Ole-enriched leaf extract, again, with RAD001, as shown via MTT assay and using the clonogenic assay." (PMID 30544808, 2018). "The initial responsiveness of mutant BRAF melanoma patients to RAF and/or MEK inhibitors varies substantially and is influenced by tumor microenvironment and adaptive resistance." (PMID 29295999, 2018). "The results of the present study indicate that rMETase has general clinical potential to improve the outcome for both diseases as non-BRAF-V600E melanoma is also sensitive to rMETase." (PMID 29541401, 2018). "Combination treatments with dabrafenib and MEK1/2 inhibitors have shown efficacy against BRAF V600E melanoma, but acquired drug resistance also developed to these therapeutic combinations." (PMID 29568360, 2018). "Opposing AXL/MITF expression in melanoma subsets has gained recent interest, because MITF-low/AXL-high expression signatures were found in tumors of a subgroup of melanoma patients resistant to BRAF/MEK inhibitor treatment." (PMID 29614062, 2018). "Research in melanoma has suggested the strategy of introducing anti-PD1 therapy before resistance to BRAF inhibitor therapy is expected to develop." (PMID 29996921, 2018). "All these drugs showed modest toxicity profiles; attentionis thus directed to their potential use in combinational regimens with other drugscommonly employed in melanoma treatment like BRAF and MEK inhibitors." (PMID 29552325, 2018). "Vemurafenib and dabrafenib, approved by the FDA in 2011 and 2013, respectively, improved OS and PFS of metastatic or unresectable melanoma patients when compared with dacarbazine and preferentially inhibit the V600E mutant form of BRAF over the wild-type form." (PMID 29455659, 2018). "Melanoma therapy has been recently directed toward immunotherapy and specific BRAF V600E inhibitors." (PMID 30279592, 2018).
melanoma (continued). "Current first-line therapy for stage IV melanoma generally includes either a checkpoint inhibitor or a BRAF/MEK tyrosine kinase inhibitor combination for patient’s bearing tumors that carry a V600E or V600K BRAF mutation." (PMID 29943192, 2018). "Prior work showed that 17-AAG inhibits cell growth in BRAFV600E and BRAF wildtype (BRAFWT) melanomas, although there were conflicting reports about the dependence of BRAFV600E and BRAFWT upon HSP90 activity for stability." (PMID 29481571, 2018). "CDK16 has also been suggested as a therapeutic target in BRAF‐mutant melanoma with increased expression of the protein reported in melanoma metastases compared to benign nevi." (PMID 29112787, 2018). "The combination of vemurafenib (BRAF inhibitor) and metformin showed encouraging results with synergistic effects for inducing melanoma cell death." (PMID 30186236, 2018). "Immunohistochemical staining of USP28 and BRAF was performed on melanoma tissue microarrays containing cores from 98 individual primary melanomas." (PMID 29880484, 2018). "Exosomes derived from a BRAF (V600) mutation have been reported to harbor a different payload compared to exosomes from wild-type BRAF melanoma cells." (PMID 30150674, 2018). "For example, BRAF inhibitor-resistant melanoma cells are more sensitive to arginine deprivation as compared to parental cells." (PMID 30456204, 2018). "Increased MAPK reactivation has been frequently observed in progressing melanomas, providing the rationale for the co-targeting of BRAF and downstream MEK." (PMID 29682188, 2018). "For example, in BRAF inhibitor‐sensitive melanoma cell lines, the preclinical version of vemurafenib, PLX4720, led to a rapid induction of ATF‐4." (PMID 29193645, 2018). "Our study provides different insights into the function of ABCB5 in melanoma chemoresistance to BRAF inhibitor." (PMID 29929490, 2018). "Modulating MDSCs using depleting antibodies (anti-Gr-1) or blocking their recruitment (CCR2 antagonist) prohibited the outgrowth of these BRAF resistant melanoma tumors." (PMID 30233579, 2018). "The introduction of BRAF inhibitors (BRAFi), such as vemurafenib and dabrafenib, as standard of care for the treatment of BRAF‐mutant melanoma has significantly improved the response rate among patients." (PMID 29507054, 2018). "Additional published work confirmed the requirement of ROS in the killing of melanoma cells following inhibition of MEK or mutant BRAF." (PMID 29624862, 2018). "The highly-selective BRAFV600E inhibitor, PLX4032 (vemurafenib), inhibits ERK signaling and cell growth in mutant BRAF melanoma cells, but paradoxically enhances signaling in cells with wild-type BRAF." (PMID 29481571, 2018). "For example, selective RAF inhibitors such as vemurafenib have demonstrated clinical efficacy in BRAF V600E mutant melanomas." (PMID 29880484, 2018). "We have found that BRAF melanoma cells exposed to a low extracellular pH medium acquired a resistance to both BRAF and MEK inhibitors but were still sensitive to the inhibition of the AKT/mTOR pathway induced by RAD001." (PMID 30544808, 2018). "The development of resistance to BRAF inhibitors is a major obstacle in targeted therapy for melanoma." (PMID 29743521, 2018). "Anti-PD-1 and BRAF-inhibitors (BRAFi) have been approved as first-line treatments in advanced melanoma." (PMID 29970025, 2018). "We validated the EMT like signature using primary melanoma cells derived from cerebral metastases with different response based on the IC50 to BRAF and MEK inhibitors." (PMID 29541007, 2018). "Second, we expanded our cell line panel and included BRAF, and ‘wild type’ melanoma cells including GNAQ and c-KIT mutants." (PMID 30405888, 2018). "To compare the effectiveness of Chk1 inhibitors on different melanoma cells, we generated BRAF inhibitor PLX4032 resistant melanoma cell lines (A375-PLX-R and WM9-PLX-R) from A375 and WM9 respectively." (PMID 30100999, 2018).
melanoma (continued). "BRAF usually serves as a biomarker for many tumors, including colorectal cancer, urachal carcinoma and melanoma cells." (PMID 30008754, 2018). "Targeted therapy with BRAF and MEK inhibitors is associated with significant long-term treatment benefit in patients with BRAF V600-mutated melanoma." (PMID 29148538, 2018). "A recent report showed that melanoma brain metastases showed a progression pattern characterized by a high propensity to disseminate in patients treated with BRAF-inhibitors." (PMID 29716947, 2018). "Increased mitochondrial biogenesis and elevated OXPHOS contribute to the resistance of melanoma to BRAF inhibitors." (PMID 29534029, 2018). "New, recently approved drug modalities like BRAF-MEK and immuncheckpoint inhibitors improved the prognosis of high risk-melanoma patients (DFS HR.47-.72) markedly." (PMID 29899854, 2018). "A previous study denotes that drug holiday-induced sensitivity towards the same therapy is due to an oncogene-induced senescence-like state by supra-physiological levels of BRAF-MEK-ERK1/2 signalling in melanoma." (PMID 29492189, 2018). "What’s more, we found that ISL remarkably suppressed the proliferation of MEWO, a cell line of BRAF wild type melanoma." (PMID 30081934, 2018). "LY3009120 inhibited the proliferation of melanoma cells with either BRAF or NRAS and colorectal cancer cells with BRAF and KRAS mutations by inducing G0/G1 cell cycle arrest." (PMID 29455659, 2018). "Initial response rates are high in patients with BRAF mutant melanoma treated with a BRAF inhibitor such as vemurafenib, but resistance nearly always develops and disease progression ensues." (PMID 29929490, 2018). "AZ304 exhibited anti-proliferative effects on multiple cancer types, including melanoma, colorectal cancer, leukaemia, ovarian cancer, lung cancer, and pancreatic cancer, independently of BRAF genetic status." (PMID 29755114, 2018). "We carried out droplet digital polymerase chain reaction to detect BRAF and NRAS mutations in plasma taken after surgery from 161 stage II/III high-risk melanoma patients enrolled in the AVAST-M adjuvant trial." (PMID 29112704, 2018). "Studies have shown that low level of endogenous MITF activity is oncogenic with BRAF (V600E), which also promotes melanoma progression." (PMID 30544544, 2018). "An inhibitor of the BRAF V600E mutant works for a few hours in melanoma, colorectal, and thyroid cancer." (PMID 30518036, 2018). "The BRAF and NRAS mutations are mutually exclusive in melanomas, suggesting that mutation in single gene locus is enough to over-activate the downstream Extracellular signal-regulated kinase (ERK) pathway." (PMID 30544544, 2018). "In other studies, fisetin was found to potentiate sorafenib-induced apoptosis and abrogate tumor growth in mice implanted with BRAF-mutant melanoma cells." (PMID 30356079, 2018). "Current therapies for advanced melanoma typically include BRAF (BRaf proto-oncogene, serine/threonine kinase) and MEK (mitogen-activated protein kinase)-targeted agents and/or checkpoint-targeted immunotherapy (ipilimumab, pembrolizumab, and nivolumab)." (PMID 29943192, 2018). "The efficacy of TRX-E-009-1 (solubilized in solutol), alone or in combination with Dabrafenib was investigated in a subcutaneous mouse xenograft model of BRAF mutant (BRAFV600E) melanoma (A375)." (PMID 29572477, 2018). "Patients, with BRAF (V600) in 40–60% of melanomas, can be successfully cured with selective inhibitors, bringing about significant prolongation of progression free survival and overall survival." (PMID 29976230, 2018). "Despite new targets presented herein, the question about sequencing immunotherapy and targeted therapy in BRAF V600-mutant melanoma patients remained unsolved." (PMID 30595751, 2018). "In human melanoma xenografts, a BRAF inhibitor, with anti-proliferative and anti-metastatic properties, inhibited CXCL8 synthesis." (PMID 29977225, 2018).
melanoma (continued). "To assess the effects of leptin in the tumor microenvironment, we generated an aggressive PTEN/BRAF melanoma line overexpressing leptin, as well as an oncolytic strain of Vaccinia virus engineered to induce tumor-specific secretion of leptin." (PMID 30400822, 2018). "For example, continued BRAF inhibitor treatment results in tumor metastasis of RAS- and BRAF-mutant melanoma cells and paradoxical activation of the RAS-ERK pathway in multiple myeloma clones." (PMID 29764517, 2018). "Most of the available literature regarding the survival of melanoma patients with brain metastasis was published prior to 2011, when BRAF inhibitor-based therapies and checkpoint inhibitors became available as standard therapies for advanced melanoma." (PMID 29703161, 2018). "The selective BRAF inhibitor vemurafenib has produced a dramatic response rate (> 50%) in BRAF-mutant metastatic melanomas, and is currently used as the standard of care for this disease." (PMID 30559933, 2018). "This synergism was also observed in BRAFV600E mutant melanoma that had acquired resistance to BRAF inhibition." (PMID 29464063, 2018). "In patients with BRAF-wild type melanoma, the investigators reported an objective response of 61% (95% CI: 49–72) as opposed to 11% (95% CI: 3–25) with combination checkpoint inhibition and ipilimumab monotherapy, respectively." (PMID 29769148, 2018). "BRAF mutations were found in 0 and 10% of in situ and early radial growth phase (RGP) melanomas, respectively 30,31." (PMID 29426936, 2018). "Recently a case of an 80-year-old man with stage IV BRAF wild type melanoma treated with nivolumab who developed signs and symptoms consistent with RS3PE after the initiation of nivolumab was reported." (PMID 29478412, 2018). "As an important mediator of adaptive resistance to RAF inhibitors, FOXD3 depletion promotes the cytotoxic effect of RAF inhibitors in mutant BRAF melanoma cells." (PMID 29295999, 2018). "The present study has demonstrated the efficacy of rMETase and the combination of rMETase and TEM on a BRAF-V600E-negative melanoma PDOX model." (PMID 29416666, 2018). "In this study, we investigated the effect of BRAF/MEK inhibition in drug-responsive melanoma cells on the induction of SASP-like secreted factors." (PMID 30237393, 2018). "In melanoma cells, the expression of 59 hypermethylated genes in the BRAF V600E knockdown were down-expressed suggesting that in mutated cells these genes were hypomethylated and over-expressed." (PMID 30454026, 2018). "Since this classification model uses only the BRAF mutant melanoma cell lines, it is difficult to generalize to all cancer types." (PMID 29560824, 2018). "While some of the older chemotherapeutic treatments for melanoma are considered outdated in light of the immunotherapies and BRAF checkpoint inhibitors, the body of evidence shows that the older therapies do have value." (PMID 30651933, 2018). "We have previously identified leflunomide as having therapeutic value in treating melanoma in a mouse xenograft model both on its own and in combination with a BRAF inhibitor." (PMID 29423085, 2018). "In a pivotal phase III randomised trial in patients with BRAF-mutant melanoma, vemurafenib achieved an objective response rate of 48% and median PFS of 5.3 months versus 5% and 1.6 months with dacarbazine, respectively." (PMID 28103611, 2017). "Taken together, these results demonstrate that NRF-1 is responsible for BRAF/MEK-mediated regulation of CD47 expression in melanoma cells." (PMID 29050218, 2017). "Comparing melanoma tumours collected before BRAF inhibitor therapy to resistant tumours in the same patient after therapy identified acquired NRAS mutations in many of these tumours, including in tumours that continue to harbor the BRAF mutations." (PMID 28282860, 2017). "In this study, we indicated that coexistence of BRAF V600E mutation and EZH2 gain is rather prevalent in melanoma." (PMID 29202777, 2017).
melanoma (continued). "Mutations in the BRAF (B-Raf proto-oncogene, serine/threonine kinase) and NRAS (neuroblastoma rat sarcoma viral oncogene) have been identified as key drivers in melanoma progression." (PMID 28522871, 2017). "Downstream increases in ERK and AKT phosphorylation were also observed, suggesting that changes in total MET and GAB1 prime BRAF mutant melanoma cells for HGF-mediated rescue via downstream activation of the PI3K and MAPK signaling pathways." (PMID 28147313, 2017). "Irrespectively, these results demonstrate that high levels of CD47 are obliged for protection against macrophage phagocytosis of melanoma cells that express increased levels of CRT on the surface after exposure to BRAF/MEK inhibitors." (PMID 29050218, 2017). "In contrast to BRAF mutated melanoma, the clinical and molecular characteristics of NRAS mutated melanoma subtypes are less well documented." (PMID 28522871, 2017). "For example, resistance to Vemurafenib (a BRAF (B-Raf Proto-Oncogene, Serine/Threonine Kinase) kinase inhibitor) frequently arises in melanoma by oncogenic re-activation of a downstream mitogen activated protein kinase (MAPK) signaling pathway member." (PMID 29104272, 2017). "Animal studies have found that mutations in the BRAF gene result in down regulation of cGMP-specific phosphodiesterase PDE5A, which lead to an increase in colonization of the lungs by melanoma cells." (PMID 28515348, 2017). "In this regard it is important to point out that some miRNAs, such as miR-638 and miR-579-3p, have been also described to affect melanoma cell apoptosis alone or in presence of BRAF inhibitors treatments." (PMID 28118616, 2017). "For further evaluation of a possible clinical benefit of RSK inhibition in therapy resistance of melanoma patients, we used tumour cells derived from two BRAF inhibitor refractory melanoma patients." (PMID 28415756, 2017). "We tested each of these drugs both alone and in combination in the mutant BRAF melanoma cell line MALME-3M at low, medium, and high concentrations, estimated from their GI10, GI25, and GI50 values respectively." (PMID 28085880, 2017). "In order to compare NGS with conventional molecular testing under routine laboratory conditions, we calculated the turn-around time and costs for three commonly melanoma-related genes (BRAF, NRAS, KIT) in eight samples." (PMID 28356599, 2017). "Metformin also induced increased survival, accelerated tumor growth and increased VEGF-A in BRAF V600 mutant melanomas." (PMID 28278159, 2017). "Simultaneous inhibition of mutant BRAF and autophagy efficiently induced caspase 3 cleavage in 7 melanoma cell lines, which mimicked the phenotype of cells with loss of MerTK when exposed to BRAFi stress as previously observed." (PMID 29050198, 2017). "Another phase I/II study (NCT02130466) is recruiting melanoma and other solid tumor patients using BRAF inhibitor and MEK inhibitor with a combination of Pembrolizumab." (PMID 28878676, 2017). "Targeting of MAPK-dysregulated tumors first showed therapeutic promise in BRAFV600-mutant metastatic melanomas with BRAF inhibitors." (PMID 28982154, 2017). "Selective inhibitors of mutant BRAF, including dabrafenib and vemurafenib, improve the progression-free and overall survival of BRAF-mutant melanoma patients." (PMID 28503307, 2017). "The suppression of MAPK signaling by inhibiting BRAF has been observed to be an effective therapeutic strategy in BRAF V600-mutant melanomas." (PMID 28416755, 2017). "Patients with tumours that carry the BRAFV600E mutation display a less promising prognosis compared to those with a wild type BRAF, in particular, in melanoma, colorectal cancer, and thyroid cancer." (PMID 28282860, 2017).